IL10 (interleukin 10)
Diseases named in the same sentence as IL10 in open-access papers (continued):
Sharing a sentence is not in itself a finding about the gene and the disease.
anemia (118 papers, 2008 to 2026). A reduction in the number of red blood cells, the amount of hemoglobin, and/or the volume of packed red blood cells. "Abnormally high levels of TNF and IL-10 have also been associated with P. falciparum malaria anaemia due to their suppressive effect on the bone marrow." (PMID 40406565, 2025). "A pre-clinical study reported that African children with severe anemia caused by P. falciparum display lower IL-10 levels than patients with moderate anemia, suggesting that IL-10 plays an important role in preventing severe cases." (PMID 37545509, 2023). "Another study also suggested that the serum hepcidin levels were associated with the IL-6 and IL-10 levels in anti-inflammatory processes and determined the anemia status of patients." (PMID 36668942, 2023). "This is supported by the observation that low levels of IL-10 together with high levels of TNF-α have been associated with anemia and cachexia." (PMID 36093199, 2022). "Elevated levels of the anti-inflammatory cytokine IL-10 in placental plasma were associated with PM, and were implicated in the pathogenesis of severe anaemia." (PMID 33422078, 2021). "Our data shows that hepatocyte-derived IL-10 is mandatory for host survival and is crucial for the control of trypanosomosis-induced inflammation and associated immunopathologies such as anemia, hepatosplenomegaly and excessive tissue injury." (PMID 32012211, 2020). "Model 3 showed an anemia risk in the covariable Ifng x Nos2 of 37.32, but the covariable Il10 presented an RR value of 0.05, indicating a protective value." (PMID 28362822, 2017). "On the other hand, injecting NZB mice with plasmids encoding IL-10 (pIL-10) delayed the development of anemia." (PMID 28455817, 2017). "Hereby, T. brucei infected galectin-3 deficient mice exhibit greatly reduced anemia levels coinciding with a restored iron homeostasis and an increased IL-10 level that in turn leads to reduced liver destruction." (PMID 26090446, 2015). "Inadequate IL-10 levels have been implicated in the pathogenesis of severe anaemia and levels of IL-10 were found to be lower in placentas from P. falciparum-exposed women than from unexposed women." (PMID 24180253, 2013). "An elevated ratio of IL-10 to TNF in the serum is associated with a decreased severity of anaemia in Kenyan children." (PMID 23282136, 2013). "Systemic and long‐term delivery of IL‐10 has been associated with flu‐like symptoms, anemia, thrombocytopenia, elevated liver transaminase levels, and injection site reactions, emphasizing the need for novel and directed IL‐10 administration strategies." (PMID 39980189, 2025). "Furthermore, the positive association of IL-10 with anemia recovery supports the notion that immune regulation contributes to the resolution of anemia in fur seal pups, mirroring findings from infections of humans with hematophagous parasites." (PMID 41306959, 2025). "Here, the reduced anemia could be associated with the high serum levels of IL-10, and IL-12 and the deficiency of TNF-α, IFN-γ and MIF." (PMID 36093199, 2022). "This notion was strengthened by the fact that interfering with MIF signaling using a Nb-based approach indeed attenuates the excessive inflammatory immune response as well as the most prominent pathological feature associated with T. congolense infections, i. e. anemia, in TgAlbCre-IL10-/- mice." (PMID 32012211, 2020). "In addition, administration of the plasmids encoding IL-10 (pIL-10) delayed the development of anemia in NZB mice as judged by increased haematocrit values compared with controls." (PMID 28455817, 2017). "Deficiency of IL-10 has been shown to induce anemia and other hematopoietic anomalies." (PMID 28415569, 2017). "The low IL10/TNFα ratio has been associated with severe anemia in young children." (PMID 27034825, 2016).
anemia (continued). "To determine whether parasite-induced anemia could have an additive effect with parasite-induced IL-10, we determined the effects of anemia and IL-10, both individually and in combination, on susceptibility to systemic S. Typhimurium infection." (PMID 24787713, 2014). "The contrasting association between anaemia and reduced HLA-DR expression on DC, on the other hand, might plausibly reflect the known suppressive effects of IL-10 - present at significantly higher levels in the plasma of infected women - in this context." (PMID 23239967, 2012). "DSS-exposed IL-10-deficient and WT animals all lost weight and developed anemia due to blood loss." (PMID 22315509, 2012). "Although the precise mechanisms underlying Treg cell-mediated protection against bone marrow pathology are currently unclear, a contribution of Treg cell-derived IL-10 was excluded, given that anemia development was comparably suppressed by either wild-type or IL-10-deficient Treg cells." (PMID 19006695, 2008). "Further studies involving IL-10 knockout mice in our experimental setting may contribute to a deeper understanding of the interaction between IL-10, anaemia and iron supplementation for infection control, given the known associations between IL-10 and iron dysregulation in inflammation." (PMID 34488018, 2021). "We showed that IL-10 knockout (IL10-KO) mice exhibited more severe anaemia, with a reduction in iRBCs in the BM and the spleen." (PMID 41471231, 2025). "Using both genetic and pharmacological approaches, we show that IL-10 is essential to limit acute anaemia by dampening inflammation and promoting splenic erythropoiesis, enabling recovery." (PMID 41471231, 2025). "Given that it was shown that IFN-γ is a driver of acute anaemia, by promoting erythrophagocytosis, the recovery from acute anaemia seems to rely more on IL-10." (PMID 41471231, 2025). "In this context, IL-10 emerges as a key anti-inflammatory cytokine that helps mitigate the severity of anemia during the course of infection." (PMID 41471231, 2025). "Together, these results demonstrate that IL-10 is key in dampening anaemia of inflammation by promoting erythropoiesis within the BM and spleen following African trypanosome infection." (PMID 41471231, 2025). "Coefficients for the effects of changes in IFN-γ, IL-6, IL-10 and neutrophils on the likelihood of recovery from anemia." (PMID 41306959, 2025). "By using both IL-10 knockout (IL10-KO) mice and anti-IL-10R-blocking antibodies, we assessed the role of IL-10 in acute anaemia during AT and found that disrupting IL-10 signaling consistently exacerbated anaemia compared to the control mice." (PMID 41471231, 2025). "The biological plausibility of bleeding and anemia in VL cases is correlated with increased levels of pro-inflammatory cytokines: IL-8, IL-1β, IL-10, and IFN-γ, which are also exacerbated in cases of bacterial coinfection." (PMID 38422344, 2024). "A possible explanation would be that patients with a higher level of LDH also have a higher concentration of IL-10, which stimulates increased production of hepcidin, involved in the pathogenesis of anemia from chronic diseases." (PMID 39071078, 2024). "During P. falciparum infection in humans, high quantities of IL-10 are associated with an inability to clear the parasite, while reduced amounts of IL-10 contribute to severe anemia." (PMID 37843306, 2023). "Similar to studies in pre-clinical models, African children with severe anaemia had lower plasma IL-10 levels than patients with moderate anaemia or cerebral malaria, suggesting that IL-10 plays an important role in preventing severe anaemia." (PMID 35464430, 2022). "With iron supplementation, anaemia additionally correlated with increased splenic levels of the cytokine IL-10, which is suggestive for a weakened immune control to S.Tm infection." (PMID 34488018, 2021).
anemia (continued). "VL patients, however, release inadequate IFN-γ and develop various clinical conditions such as splenomegaly pancytopenia, anemia and disseminated hemorrhages in the presence of excess IL-10 production." (PMID 32555598, 2020). "Maternal anemia was also associated with cytokine responses in cord (particularly for MDP and LPS), with higher IL-10, IL-1β, MDC, TNF, IL-12p70, IL-12p40 responses following PRR stimulation." (PMID 32765436, 2020). "Similar to studies in pre-clinical models, African children with severe anemia had lower plasma IL-10 levels than patients with moderate anemia or cerebral malaria, suggesting that IL-10 plays an important role in preventing severe anemia." (PMID 30809232, 2019). "IL-10 is known to induce thrombocytopenia and anemia and it also inhibits human mononuclear cell expression of MIP-1 proteins; both MIP-1α and MIP-1β." (PMID 30949167, 2019). "By contrast, in the less aggressive model experimental PLC−/−T. brucei C57BL/6 model, there is a switch from M1 toward M2 mediated via IL-10, coinciding with reduced pathology (anemia/tissue injury) and prolonged survival." (PMID 29497418, 2018). "Alternatively, adenoviral delivery of IL-10 in the T. brucei model coincided with an alleviated pathology/anemia development, during the chronic phase of infection." (PMID 29497418, 2018). "Different factors were found to contribute to the ability of the host to switch from M1 to M2 and the ability to maintain/trigger IL-10 during the later stages was shown to be detrimental to attenuate anemia." (PMID 29497418, 2018). "The results of logistic regression analysis suggest that increased splenic Tgfb and Il10 expression levels are protective in anemia of inflammation." (PMID 28362822, 2017). "Contrary to these findings, severe anaemia in falciparum malaria has been associated with high concentrations of TNF-α and low concentrations of IL-10, with the ratio between them being the clearest indicator of disease severity." (PMID 26953797, 2016). "In the absence of malaria parasite infection, administration of recombinant IL-10 together with induction of anemia had an additive effect on systemic bacterial colonization." (PMID 24787713, 2014). "Plasma levels of IL-10 were negatively correlated with parity and positively with poor pregnancy outcome (high parasitaemia, severe anaemia, abortion, and pre-term delivery) in the mouse model used here." (PMID 24180253, 2013). "While IL-6 and INF-γ are known to suppress erythropoiesis, TNF and IL-10 are thought to contribute to the degree of anaemia in children with falciparum malaria." (PMID 23978045, 2013). "High levels of IL-10 were also detected in African and Indian children with anaemia and high levels of parasitaemia." (PMID 24359168, 2013). "This is supported by the observation that anaemia is increased in IL-10 knockout mice infected with Plasmodium chabaudi and reversed upon TNF neutralization." (PMID 22853732, 2012). "Although both groups developed similar levels of anaemia, mice that received IL-10−/− T cells lost significantly more weight and succumbed to infection more rapidly than mice that received WT CD4+ T cells." (PMID 18401464, 2008). "PyNL infection was significantly attenuated - with significant reductions in parasitaemia and anaemia in IL-10−/− mice compared with WT mice, although the IL-10−/− mice did lose significantly more weight than age-matched WT mice." (PMID 18401464, 2008). "CECs also accumulate in patients with infections, tumors, and anemia, and effectively suppress T cells by producing high levels of arginase, reactive oxygen species, programmed death-ligand 1, transforming growth factor β, and/or interleukin-10." (PMID 39474425, 2024). "The repeated associations between anemia and cytokines and chemokines, such as IL-10, IL-8, and CXCL1-like, indicate that increased production of IL-8 and CXCL1-like, and/or insufficient production of IL-10, can have an influence on phagocytic anemia in canine babesiosis." (PMID 36839438, 2023).
anemia (continued). "In severe anemia, low IL-10 levels might allow patients to produce enough TNF to interfere with erythropoiesis and erythrophagocytosis." (PMID 36668942, 2023). "Moreover, the frequencies of circulating IFN-γ+ and IL-10+ MAIT cells were associated with a lower hemoglobin level, indicative of severe anemia." (PMID 36189274, 2022). "Thus, IL-10 can be considered a marker for dangerous placental inflammation and levels of IL-10 correlated with maternal anemia." (PMID 33391279, 2020). "IL-10 suppresses inflammation by suppressing various cytokines, including IL-1β and TNFα, which is also a mechanism involved in down-regulating hepcidin expression and alleviation of anemia." (PMID 30836628, 2019). "Regression analysis revealed that HO-1 was associated with haemolysis, but not with parasite density, anaemia or IL-10 concentration." (PMID 29980206, 2018). "The serious side effects that occur in IL-10 therapy are anemia and thrombocytopenia." (PMID 29765083, 2018). "It is important to mention that following this prominent pro-inflammatory immune response and coinciding with the partial recovery of acute anemia, the host is able to trigger a “transient” anti-inflammatory immune response, whereby IL-10 was shown to play a key role." (PMID 29497418, 2018). "Also, the severity of anemia has been suggested to be dependent on levels of TNF-α relative to anti-inflammatory cytokine IL-10." (PMID 29034874, 2017). "Inflammatory cytokines such as interferon-γ, tumor necrosis factor-α, interleukin-1, and interleukin-10 might compromise iron metabolism, impair erythroid progenitor cell proliferation, and blunt erythropoietin response to anemia." (PMID 29237417, 2017). "However, we have previously shown that phagocytized PfHz promotes overproduction of IL-10,in turn suppressing IL-12, thereby exacerbating anemia and slowing parasite clearance." (PMID 27418744, 2016). "Moreover, a GPI-based intervention strategy was found to alleviate trypanosomosis-associated anemia development by lowering the proinflammatory cytokine production (including TNF, MIF, and Gal-3) and increasing IL-10 production." (PMID 26090446, 2015). "Our data suggests one explanation for these apparently surprising observations, namely therapeutic IL-10 in these patients may have induced high levels of hepcidin leading to anaemia." (PMID 24520384, 2014). "These different syndromes might be associated with specific immune responses: for example, children with severe anemia have lower IL-10 levels compared to children with cerebral malaria." (PMID 24130857, 2013). "Similarly, IL-10−819CT and TT genotypes as well as the IL10-ATA haplotype (one or two copies) were positively related to anaemia in newborns." (PMID 23668806, 2013). "The high TNF/IL-10 ratio observed in SMA suggests an imbalanced production of inflammatory cytokines that could contribute to anaemia." (PMID 22853732, 2012). "However, the role of IL-10, a key anti-inflammatory cytokine in regulating stress-induced acute anaemia during African trypanosomosis (AT), remains unclear." (PMID 41471231, 2025). "Interestingly, IL-10 emerged as a potential protective factor in pups that recovered from anemia." (PMID 41306959, 2025). "Thus, it seems possible that immunosuppressive IL-10, or rather its insufficient production, may play a role in the development of anemia in canine babesiosis." (PMID 36839438, 2023). "For example, TNF-α overproduction — which can result from a deficit of anti-inflammatory cytokines like interleukin 10 (IL-10) and transforming growth factor-beta (TGF-β) — could lead to adverse effects including worsened anaemia, weight loss and survival in the mouse model." (PMID 34636723, 2021). "Moreover, the increased hepatosplenomegaly in TgAlbCre-IL10-/- mice leads to hemodilution, which in combination with a reduced erythropoiesis aggravates one of the most prominent immunopathological features of T. congolense-infected animals: anemia." (PMID 32012211, 2020).
anemia (continued). "IL-10 but not IL-33 has been linked to lower ferritin levels and anemia." (PMID 31333751, 2019). "KICS is a newly described condition that typically manifests with fever, anemia, thrombocytopenia, hypoalbuminemia, hyponatremia, hepatosplenomegaly, elevated CRP, and increased IL‐6 and IL‐10 levels, along with a high HHV‐8 viral load." (PMID 41424756, 2025). "Blood gas analysis showed dilutional anemia during V-V ECMO, whereas plasma analysis revealed a decreased concentration of IL-10 during V-V ECMO therapy, and BAL measurements showed increased concentrations of TNF-α, CXCL2, and CXCL5." (PMID 38928327, 2024). "Comparisons of patients with mild TB and mod-sev disease or anemia, demonstrated that Th1 (IL-2, IFN-γ, and TNF-α) as well as Th2 (IL-4, IL-13, and IL-10) and Th17 responses were higher in mild TB disease." (PMID 38162636, 2023). "The frequencies of IFN-γ+ and IL-10+ MAIT cells were inversely correlated with Hb levels, a marker of severe anemia." (PMID 36189274, 2022). "Collectively, blocking MIF in TgAlbCre-IL10-/- mice, using an anti-MIF Nb, was found to attenuate anemia and excessive systemic inflammatory cytokine levels, without affecting parasite burden." (PMID 32012211, 2020). "Mice were administered recombinant IL-10 (rIL-10), or anti-red blood cell (α-RBC) IgG to induce anemia, or received both treatments." (PMID 24787713, 2014). "Without IL-10, uncontrolled inflammation disrupts both BM and splenic erythropoiesis, exacerbating infection-induced anaemia." (PMID 41471231, 2025). "The frequency of TGF-β (T/T-G/G and T/C-G/G, 80% vs. 59%, p = 0.03) and IL-10 (GCC-GCC, 16% vs. 5%, p = 0.02) high gene expression level genotypes was higher in patients with more severe anemia (Hb ≤7.5 g/dL, i.e., median of all AIHA) versus the remaining AIHA population." (PMID 38022547, 2023). "Cytokines IFN-γ and TNF-α were shown to be involved in exacerbation of anemia as mice lacking the respective genes exhibited protection from anemia, while anti-inflammatory cytokine, IL-10 counteracted the effects of Trypanosoma-induced anemia." (PMID 36504775, 2022). "Furthermore, the frequencies of IFN-γ+ and IL-10+ MAIT cells were inversely correlated with hemoglobin levels, a marker of severe anemia." (PMID 36189274, 2022). "It was observed from this analysis that the group of individuals with anemia had higher levels of IL-6, TNF- α, and IL-10 cytokines than the individuals without anemia (P < 0.05)." (PMID 35749690, 2022). "Based on these findings, banking P. falciparum-infected blood could exacerbate preexisting anaemia in blood recipients, through inhibition of erythropoietin activity by high TNF-α levels and low IL-10 levels." (PMID 33195706, 2020). "While neither anaemia nor HPX were significantly associated with mortality, high levels of plasma haem, IL-10 and HO-1 at admission were significantly associated with risk of dying." (PMID 30046137, 2018). "On the other hand, higher IP-10/CXCL10 plasma levels, as well as IFN-γ and IL-10, were observed in vivax malaria patients with mild anaemia in comparison to no anaemia." (PMID 28118834, 2017). "Laboratory abnormalities include anaemia, thrombocytopenia, hyponatremia, hypoalbuminaemia, and elevations of C-reactive protein (CRP), KSHV viral load, interleukin-6 (IL-6), and interleukin-10 (IL-10)." (PMID 26242311, 2015). "Specifically, South American fur seal pups that failed to recover from hookworm-associated anemia had sustained higher concentration of neutrophils, IFN-γ, and IL-6, while those that recovered showed decreases in these markers and increased IL-10 concentration." (PMID 41306959, 2025). "Consequently, timely adjustment of the IL-10/IFN-γ balance may enhance erythropoiesis and offer a potential therapeutic strategy to mitigate anaemia development." (PMID 41471231, 2025). "Active VL could also explain the negative correlation we observed between IL-10 and hemoglobin levels, since anemia is a frequent finding in patients with VL." (PMID 35714136, 2022).